CEACAM5 (CEA cell adhesion molecule 5)
Description:
Cell surface glycoprotein that plays a role in cell adhesion, intracellular signaling and tumor progression. Mediates homophilic and heterophilic cell adhesion with other carcinoembryonic antigen-related cell adhesion molecules, such as CEACAM6. Plays a role as an oncogene by promoting tumor progression; induces resistance to anoikis of colorectal carcinoma cells. (Microbial infection) Receptor for E.coli Dr adhesins. Binding of E.coli Dr adhesins leads to dissociation of the homodimer.
Synonyms: CEA; CD66e
Tractability: Small molecule: a structure with a bound ligand is known. Antibody: an approved drug acts on it; UniProt places it where antibodies can reach, with high confidence; its Gene Ontology location is reachable by antibodies, with high confidence; UniProt predicts a signal peptide or a membrane-spanning region; the Human Protein Atlas places it where antibodies can reach. Other modalities: a drug acting on it is in phase 2 or 3 trials.
Target class: Adhesion
Gene: Protein-coding gene on chromosome 19 (41,708,585 to 41,730,519, forward strand). Ensembl gene ENSG00000105388.
Subcellular location: Cell membrane; Apical cell membrane; Cell surface
Subcellular location (Human Protein Atlas): Plasma membrane
Pathways (Reactome):
Hemostasis: Cell surface interactions at the vascular wall
Metabolism of proteins: Post-translational modification: synthesis of GPI-anchored proteins
Gene Ontology:
Molecular function: GPI anchor binding; identical protein binding; protein binding; protein homodimerization activity
Biological process: heterophilic cell-cell adhesion; homophilic cell-cell adhesion; homotypic cell-cell adhesion; negative regulation of anoikis; negative regulation of apoptotic process; negative regulation of myotube differentiation
Cellular component: apical plasma membrane; basolateral plasma membrane; cell surface; extracellular exosome; membrane; plasma membrane; extracellular region
Genetic constraint (gnomAD): Loss-of-function variants: 51 observed, 63.97 expected, observed/expected ratio (o/e) 0.8, 90% interval 0.64 to 1.01. The upper end of that interval is the gene's LOEUF score, 1.01, which puts it in group 4 of 6, group 1 being the genes least tolerant of losing a copy. Missense variants: 787 observed, 896.73 expected, observed/expected ratio (o/e) 0.88, 90% interval 0.83 to 0.93. Synonymous variants: 357 observed, 365.74 expected, observed/expected ratio (o/e) 0.98, 90% interval 0.89 to 1.07.
Homologues: Orthologues: chimpanzee CEACAM5 (98% identical), macaque CEACAM1 (43% identical). Paralogues in human: CEACAM1 (46% identical), CEACAM6 (40% identical), CEACAM8 (37% identical), CEACAM7 (25% identical), PSG8 (24% identical), PSG7 (23% identical), PSG6 (23% identical), PSG9 (23% identical), PSG4 (23% identical), PSG1 (23% identical), PSG3 (23% identical), PSG2 (21% identical), and 12 more.
Diseases named in the same sentence as CEACAM5 in open-access papers:
CEACAM5 is named in the same sentence as 340 diseases in open-access papers, as found by Europe PMC text mining. Sharing a sentence is not in itself a finding about the gene and the disease. The quoted sentences say what the papers report.
colorectal cancer (401 papers, 1974 to 2026). A primary or metastatic malignant neoplasm that affects the colon or rectum. "CEACAM5 is a well-studied marker for colorectal cancer, and soluble CEA serves as an FDA-approved diagnostic tumor marker." (PMID 41283511, 2025). "CEACAM5 is a cell surface protein that is upregulated in colorectal cancer and has been functionally associated with tumor differentiation, invasion, and metastasis." (PMID 39948151, 2025). "A few of the Top 10 potential proteomic biomarkers revealed in our study have been previously identified as compounds associated with colorectal cancer’s response to RT, including CEACAM5, KHSRP, RALA, and TSPAN8." (PMID 38410100, 2024). "The high expression of CEACAM5 in colorectal cancer cells is closely associated with the CD133-positive colorectal cancer stem cell phenotype." (PMID 35872794, 2022). "Following the discovery of Carcinoembryonic antigen (CEA or CEACAM5) as a colorectal cancer-associated antigen, anti-CEACAM5 mAbs have been found effective in diagnosis and therapy of multiple types of cancers." (PMID 21731662, 2011). "More interestingly, mAb CC4 is able to enhance NK cytotoxicity against MHC-I-deficient colorectal cancer cells by blocking intercellular interaction between epithelial CEACAM5 and NK inhibitory receptor CEACAM1." (PMID 21731662, 2011). "In present study, we found that some HLA-I-deficient colorectal cancer cells (Lovo) present high levels of CEACAM5 and were resistant to the killings by CD16-negative NK cells." (PMID 21731662, 2011). "We observed limited availability of CEACAM5 on human colorectal cancer tissues, whereas treatment with trypsin or hyaluronidase increased accessibility." (PMID 41572139, 2026). "Here, we have studied the interaction of CEACAM5 targeting primary CAR T-cells with colorectal cancer (CRC) cells using fluorescence microscopy." (PMID 41572139, 2026). "For example, labetuzumab, a monoclonal antibody, directly inhibits CEACAM5 and is utilized in the treatment of colorectal cancer." (PMID 41049426, 2025). "CEACAM5 has been used as a tumor marker for colorectal cancer since 1965 to aid in diagnosis and monitor tumor progression." (PMID 41266534, 2025). "Recently, promising data were reported for the TopoI payload-based CEACAM5-specific antibody drug conjugate precemtabart tocentecan in a Phase 1 study in colorectal cancer patients." (PMID 41283511, 2025). "Using Random Survival Forest (RSF) analysis with importance scoring, we identified seven key prognostic genes (CD24, SLC25A5, HSPB1, CD9, SPIMK1, LGALS4, and CEACAM5), which were subsequently designated as the Colorectal cancer Survival Signature (CSS)." (PMID 40777020, 2025). "TFF3, TFF1, SELE, AHCY, LCN2, CEACAM5, and RETN are consistently upregulated across a variety of datasets and analyzes, which supports their crucial roles in the underlying mechanisms of colorectal cancer progression." (PMID 39839775, 2024). "In contrast, CEACAM5 expression is high in patients with lung adenocarcinoma, gastric cancer, and colorectal cancer and correlated with poor clinical outcomes and overall survival." (PMID 39468006, 2024). "For example, there were currently 9 trials involving CEACAM5, a tumor marker over-expressed on the surface of multiple solid tumors, such as lung cancer, colorectal cancer and gastric cancer." (PMID 39060958, 2024). "Carcinoembryonic antigen-related cell adhesion molecule 5 (CEACAM-5) is a glycoprotein overexpressed in colorectal cancer." (PMID 39839775, 2024). "The authors of article sought to assess the discriminatory capacity of a CEACAM5-targeted probe in detecting colorectal cancer (CRC) and to evaluate the utility of NIR-II imaging-guided resection in CRC." (PMID 38293525, 2024). "CEA, also known as CEACAM5 or CD66e, is a cell-surface glycoprotein anchored by glycophosphatidyl inositol, and it is found to be overexpressed in the majority of colorectal cancers." (PMID 38293525, 2024).
colorectal cancer (continued). "As a conventional tumor marker of colorectal cancer, CEACAM5 plays an important role in multiple tumors." (PMID 38686388, 2024). "CEACAM5 is now considered a reliable clinical biomarker and a promising therapeutic target for melanoma, lung cancer, colorectal cancer, and pancreatic cancer." (PMID 37234801, 2023). "CEACAM5 is expressed in multiple epithelial malignancies, including gastric cancer, colorectal cancer, and pancreatic cancer, as well as in NSC lung cancer and melanoma." (PMID 36741860, 2023). "CEACAM5 was reported to function as an oncogene by promoting tumor progression and inducing anoikis resistance in colorectal cancer, while CEACAM6 was found to be involved in the metastatic process by inducing anoikis resistance in pancreatic cancer." (PMID 37090717, 2023). "Recently, it has been demonstrated that CEACAM5 overexpression is a reliable characteristic of CD133-positive colorectal cancer stem cells." (PMID 36494785, 2022). "CEACAM-5 is also secreted in soluble form from cancer cells into the serum, and the measurement of CEACAM-5 serum levels in cancer patients is used as a parameter for the staging and follow-up of colorectal cancer." (PMID 35804808, 2022). "CEACAM5 has been widely studied in various kinds of cancers, including breast cancer, colorectal cancer, pancreatic cancer, gastric cancer, and carcinoma of the tongue." (PMID 33592582, 2021). "Since carcinoembryonic antigen (CEA; CEACAM5) is abundantly overexpressed in colorectal cancer, it is a potential target for tPDT of colorectal cancer." (PMID 31828541, 2019). "Here, we focused on tPDT in a colorectal cancer model using a humanized monoclonal antibody directed against CEA (CEACAM5)." (PMID 31828541, 2019). "Our detection of CEACAM5 in T84 cells likely reflects the increased CEACAM5 expression and altered CEACAM5 glycosylation often found in colorectal cancer." (PMID 26512888, 2015). "The finding that CEACAM5 protects tumor cells from NK killing is rather significant in colorectal cancers since a very high percentage of colonic adenocarcinomas display strong expressions of CEACAM5." (PMID 21731662, 2011). "We transfected CEACAM1- and CEACAM5-expressing plasmids into colorectal cancer HCT-15 cells, respectively, and then generated stable cell lines, designated as HCT-15/CEACAM1 and HCT-15/CEACAM5." (PMID 21731662, 2011). "High levels of CEACAM5 expression are found in human patients in 80 - 90% of all colorectal cancers, in up to 50% of all breast and lung cancers and in about 15% of gastrointestinal and pancreatic carcinomas as well as in many other epithelial cancers." (PMID 21436956, 2011). "Carcinoembryonic antigen (CEA, CEACAM5, and CD66e) has been found to be associated with various types of cancers, particularly colorectal carcinoma, and developed to be a molecular target for cancer diagnosis and therapy." (PMID 21731662, 2011). "CEACAM5, carcinoembryonic antigen-related cell adhesion molecule 5, is irreversibly up-regulated by smoking and is elevated in the serum of cancer patients with lung adenocarcinoma and colorectal cancer." (PMID 17894889, 2007). "CEACAM5, a cell surface protein, is overexpressed in colorectal cancer (CRC)." (PMID 40739424, 2025). "CEACAM5 has also been shown to be important in metastasis in colorectal cancer." (PMID 36741860, 2023). "As we revealed the interplay of various cell types including colonocytes and cycling cells in CEACAM1_CEACAM5 interaction in IBD or colorectal cancer patients, it might highlight targeting these cells to reverse the adverse conditions." (PMID 37414760, 2023). "Indeed, CEACAM5 is now considered as clinically effective biomarker and prospective target in various solid malignancies, the majority of which are colorectal cancers." (PMID 34922633, 2021).
colorectal cancer (continued). "Furthermore, somatic missense mutations in colorectal cancers have been detected in CEACAM1 and CEACAM5, the latter of which has been shown to increase proliferation by inhibiting TGFB signaling and altering the intestinal microbiome." (PMID 34447411, 2021). "Colorectal cancer expressed similar levels of CEACAM5 as normal colorectal tissue." (PMID 31897235, 2020). "Similarly, another study demonstrated the ability of an anti-CEACAM5 monoclonal antibody (CC4) to restore NK cytotoxicity in colorectal cancer preclinical models by blocking the CEACAM 5 (CEA)–CEACAM 1 axis." (PMID 32637350, 2020). "Above findings led to the possibility that mAb CC4 may interfere with the cell-cell contact between CEACAM1 expressed on immune cells and CEACAM5 expressed on colorectal cancer cells." (PMID 21731662, 2011). "Owing to its ectopic expression and correlation with metastatic potential in cancers, particularly colorectal cancer, CEACAM5 measurement has been widely applied in clinical detection of liver metastasis from colorectal cancers and post-surgical surveillance of colon cancer." (PMID 21731662, 2011). "We showed here that mAb CC4 could markedly enhance NK cytotoxicity against colorectal cancer cells by disrupting the inhibitory interaction of tumor CEACAM5 or CEACAM1 with NK CEACAM1." (PMID 21731662, 2011). "The effect of glycoengineering a membrane specific anti-carcinoembryonic antigen (CEA) (this paper uses the original term CEA for the formally designated CEACAM5) antibody (PR1A3) on its ability to enhance killing of colorectal cancer (CRC) cell lines by human immune effector cells was assessed." (PMID 19904275, 2009). "Indeed, overexpression of CEACAM5 in colorectal cancer correlates with soluble CEACAM5 concentrations in serum, and in cancer patients concentrations from 0.002 to 5.187 ug/mL have been reported, with soluble CEACAM5 values generally correlating with advanced cancer stages." (PMID 41283511, 2025). "Carcinoembryonic antigen-related cell adhesion molecule 5 (CEACAM5, abbreviated as CEA hereafter) is a well-known tumor biomarker of colorectal cancer that is highly expressed on the membranes of CRC cells." (PMID 41155143, 2025). "CEACAM5 (carcinoembryonic antigen-related cell adhesion molecule 5, also known as CEA) was reported to be a driver gene in colorectal cancer and is related to tumor differentiation, invasion and metastasis." (PMID 40362181, 2025). "Protein quantitative trait loci analyze studies provided further evidence for the involvement of TFF1, CEACAM5, and SELE in colorectal cancer, with possible connections to the PI3K/Akt and MAPK signaling pathways." (PMID 39839775, 2024). "CEACAM5 interacts with DR5, a member of the death receptor family found on the plasma membrane of colorectal cancer cells that have detached from the extracellular matrix." (PMID 39839775, 2024). "Using GMM, we showed that CEACAM5 and CEACAM6 mRNA levels in the panel of 68 colorectal cancer cell lines were bimodally distributed." (PMID 38502695, 2024). "CEACAM5 (CEA) was chosen as a CAR target because of its high expression in neuroendocrine prostate cancer, colorectal cancer, gastric cancers, and small cell cancers of the lung." (PMID 37963244, 2023). "Genes elevated in colorectal cancer metastasis included higher expression of Cadherin 17 (CDH17) and the adhesion molecules CEACAM5 and CEACAM6, previously shown to correlate with metastasis colonization." (PMID 33332768, 2020). "In present study, we show that the same tumor immune escape mechanism also exists in human colorectal cancer and mAb CC4 can significantly block the inhibition of NK cytotoxicity by interfering with the CEACAM5-CEACAM1 intercellular interaction." (PMID 21731662, 2011). "In this paper, we report a novel anti-CEACAM5 mAb, namely CC4, which specifically accumulates in tumor tissues and remarkably inhibits tumor growth of colorectal cancer both in vivo and in vitro." (PMID 21731662, 2011).
colorectal cancer (continued). "In present study, we generated a novel anti-CEACAM5 monoclonal antibody, namely mAb CC4, by immunizing mice with living colorectal cancer LS174T cells." (PMID 21731662, 2011). "On its discovery in 1965 by Gold and Freedman1 in the blood of patients with colorectal cancer, human carcinoembryonic antigen [CEA (since re-designated CEACAM5)] was initially thought to be a tumour-specific antigen." (PMID 17576469, 2007). "Seven proteins namely TFF3, LCN2, CEACAM5, TFF1, SELE, RETN, and AHCY proteins of both phases were found to be upregulated in colorectal cancer in human protein atlas database, also were significant in our UK Biobank dataset and had an essential function in CRC." (PMID 39839775, 2024). "Seven proteins, TFF3, LCN2, CEACAM5, TFF1, SELE, RETN, and AHCY were found to be upregulated in other databases and also in our UK Biobank where TFF3 and LCN2 were found to be the most significant proteins and were highly expressed in colorectal cancer." (PMID 39839775, 2024). "The expression of CEACAM5 and CEACAM6 in colon cancer cell lines is increased in the presence of proinflammatory cytokine interleukin 6, supporting an important role in inflammation in colorectal cancer." (PMID 36741860, 2023). "Thus, the tumor immune evasion mechanism that up-regulation of CEACAM1 or CEACAM5 activates inhibitory CEACAM1 signaling in NK cells and then circumvents NK cytotoxicity also exists in colorectal cancer cells." (PMID 21731662, 2011). "Currently, ADCs targeting colorectal cancer are mainly monoclonal antibody ADCs, with primary targets including human epidermal growth receptor 2 (HER2), guanylyl cyclase C (GCC), mesothelin, and carcinogenic antigen-related cell adhesion molecule 5 (CEACAM5), and so on." (PMID 40721409, 2025). "However, the function of CEACAM5 in inhibiting the killings by CD16-negative NK cells has never been tested in colorectal cancer, in which CEACAM5 displays the highest pathological expression." (PMID 21731662, 2011). "Although CEACAM5—and to a lesser extent CEACAM6—are consistently overexpressed in most colorectal cancers and have a broad range of tumorigenic effects, they have not yet been assigned to any proposed pathway." (PMID 17576469, 2007).